CDKN2A (cyclin dependent kinase inhibitor 2A)
Diseases named in the same sentence as CDKN2A in open-access papers (continued):
Sharing a sentence is not in itself a finding about the gene and the disease.
glioma (continued). "In glioma, genome-wide association studies have identified common genetic variations in 7 genes that increase glioma risk (TERT, EGFR, CCDC26, CDKN2A, CDKN2B, PHLDB1 and RTEL1) but BRCA1 is not among them and there is no known association between BRCA1 gene and glioblastoma multiforme (GBM)." (PMID 25880076, 2015). "In addition to the well-known and highly recurrent events, GTS defines and ranks many previously unrecognized CNAs, uncovers frequent codeletion of two related CKI genes, CDKN2C and CDKN2A, in human cancers, and implicates APAF1 and FBXW7 in glioma pathogenesis." (PMID 18394558, 2008). "However, the radiomic features of CDKN2A/B homozygous deletion in gliomas have not been developed, and whether the radiomic features and molecular subgroups can provide prognostic value in low-grade gliomas (LGGs) has yet to be studied." (PMID 37190513, 2023). "Numerous studies have identified the negative prognostic impact of homozygous CDKN2A deletion in adult glioblastoma and this is now incorporated into the WHO classification of grade 4 glioma." (PMID 40860828, 2025). "The results prove that homozygous CDKN2A/B deletions are strong negative prognostic markers for OS in both IDH-mut and IDH-wt gliomas." (PMID 39593128, 2024). "Fluorescence in situ hybridization (FISH) is a common ancillary testing modality used to assess CDKN2A status, but the specifics of how to best interpret FISH results for prognostication of gliomas have not been clearly defined in the literature." (PMID 33081848, 2020). "The amplification of oncogenes across LGG was not as extensive as GBM, but focal deletions of CDKN2A/B were also found in LGG, which were considered as negative cell cycle regulators in gliomas." (PMID 31719831, 2019). "Previous studies have shown that BRAF V600E and CDKN2A alterations were less commonly observed in PLGG that did not transform, but more frequently detected in secondary high grade gliomas." (PMID 29152094, 2017). "Then, because single c-Myc and Cdc20 genes are not sufficient to induce glioma in both CDKN2A+/+ and CDKN2A−/− Ntv-a mice, we explored the role of c-Myc and Cdc20 in glioma development in a RCAS/Ntv-a mouse model using the combination of kRas and Akt3." (PMID 26993778, 2016). "While in IDH wildtype glioblastoma CDKN2A deletions are nearly universally homozygous, we acknowledge that in some patients with IDH1/2mt gliomas, the CDKN2A deletion as determined by NGS may not be homozygous." (PMID 36968138, 2023). "Furthermore, glioma patients without EGFR amplification and CDKN2A deletion had the best prognosis than glioma patients with EGFR amplification or CDKN2A deletion or with both alterations in the MSKCC datasets." (PMID 33959491, 2021). "But since the vast majority of non-enhancing gliomas IDH wild type in adults are molecular glioblastomas, and that CDKN2A/B homozygous deletion is rare in the WHO grade 2 group, we believe that the results at the group level would not differ from what we have presented." (PMID 34621684, 2021).
pancreatic cancer (406 papers, 2003 to 2026). "CDKN2A is the most frequent pathogenic variant in familial melanoma and is also associated with pancreatic cancer." (PMID 40941017, 2025). "Another commonly mutated gene in pancreatic cancer is CDKN2A (> 40%), whose alterations are related mainly to cell cycle dysregulation, promoting its progression through the loss of cyclin-dependent kinase CDK4 and CDK6 inhibition." (PMID 39361216, 2025). "The germline CDKN2A mutation also confers to patients an increased risk of developing pancreatic cancer." (PMID 39420514, 2025). "CDKN2A was associated with several cancer-related pathways, including colorectal cancer, endometrial cancer, and pancreatic cancer, while HSD17B1 was enriched in metabolic and signaling pathways, such as galactose metabolism and MAPK signaling." (PMID 41226409, 2025). "In FAMMM patients, there is an estimated risk to develop pancreatic cancer 13–22 times higher than the risk in the average population, and the risk increases to more of 40‐fold in CDKN2A‐mutant FAMMM patients." (PMID 39609109, 2025). "The familial forms of CM and pancreatic cancers are often characterized by a common mutated gene, namely CDKN2A." (PMID 39609109, 2025). "The penetrance for pancreatic cancer has been estimated as 17% in CDKN2A mutation carriers by 75 years of age." (PMID 39609109, 2025). "Studies have shown the presence of the inactivate protein product of CDKN2A gene, namely p16INK4a, in 95% of sporadic pancreatic cancers; however, germline CDKN2A mutations in these cases are rare." (PMID 39609109, 2025). "Oncogenic point mutations of the KRAS gene can be detected in > 90% of pancreatic carcinomas and, along with the alterations for CDKN2A, are among the early events in carcinoma development." (PMID 39807486, 2025). "Higher CDKN2A methylation is observed in pancreatic cancer patients, making it a potential diagnostic tool, particularly when analyzed in blood, pancreatic tissue and juice samples." (PMID 38666907, 2024). "We report two families with familial pancreatic cancer with suspected pathogenic variants of CDKN2A that were incidentally identified through comprehensive genomic profiling." (PMID 38961426, 2024). "Familial atypical multiple mole melanoma (FAMMM) is an autosomal dominant genodermatosis characterized by a mutation in the CDKN2A gene, which is characterized by multiple melanocytic nevi and also an increased risk of pancreatic cancer." (PMID 39200847, 2024). "These chromosome arms contain tumor suppressor genes frequently deleted or mutated in pancreatic cancer, such as CDKN2A and SMAD4." (PMID 39700179, 2024). "Inherited pathogenic variants in the CDKN2A gene contribute significantly to pancreatic cancer susceptibility, especially in FAMMM syndrome families." (PMID 38666907, 2024). "CDKN2A mutations play a significant role in pancreatic tumors, with somatic mutations present in up to 95% of pancreatic tumors and a genetic predisposition observed in familial cases." (PMID 38666907, 2024). "Pathogenic variants in CDKN2A increase the risk for pancreatic cancer (~ 5% to 24% lifetime risk), and individuals with pathogenic variants in CDKN2A tend to have an earlier onset of cancer." (PMID 38378604, 2024). "Among individuals with a specific CDKN2A mutation undergoing early detection screening, 7.3% were found to harbor pancreatic cancer." (PMID 39064499, 2024). "CDKN2A mutations were significantly associated with increased pancreatic cancer prevalence in families." (PMID 38666907, 2024). "The impact of CDKN2A mutations on overall survival in pancreatic cancer patients is still being investigated, with some studies suggesting a potential correlation with poorer prognosis in PDAC patients." (PMID 38666907, 2024).
pancreatic cancer (continued). "A total of 537 confirmed CDKN2A PV carriers and at-risk carriers under skin and pancreatic cancer surveillance were invited for this study, of whom 247 participated." (PMID 38822936, 2024). "A prospective study for Dutch CDKN2A variant carriers reported that the outcomes of the pancreatic cancer patients were improved by the detection through surveillance (resectability: 83%, 5-year survival rate: 32%)." (PMID 38961426, 2024). "Understanding the genetic landscape of CDKN2A in pancreatic cancer provides valuable insights into risk assessment, surveillance strategies and potential targeted therapies for this challenging disease." (PMID 38666907, 2024). "Germline CDKN2A variants are present in over 3% of pancreatic tumours which demonstrates their importance in carcinogenesis." (PMID 37790705, 2023). "In the Italian population study by Ghiorzo, CDKN2A germline mutations were identified in 13 (5.7%) of 225 Italian patients diagnosed with pancreatic cancer." (PMID 38137564, 2023). "Back in 2016, it has been reported that pancreatic cancer as a malignant tumor, mutation of CDKN2A gene is an important factor for its pancreatic tumorigenesis." (PMID 36967449, 2023). "CDKN2A is a gene located at chromosome 9 which encodes proteins that control cell proliferation and their mutation increases the risk of pancreatic cancer." (PMID 37790705, 2023). "The TCGA pancancer study also teaches us that the proportion of tumors with mutated CDKN2A with respect to deletions is among the highest in pancreatic cancer (together with bladder cancer, non-small cell lung cancer, melanoma)." (PMID 36765923, 2023). "The deletion of CDKN2A was not only a diagnostic marker for a poor clinical outcome, but also it predicts metastasis of pancreatic tumor, recurrence of oral squamous cell carcinoma, and early recurrence in meningioma." (PMID 37626750, 2023). "Mutations in the CDKN2A gene present one of the most prevalent causes of increased susceptibility to pancreatic cancer." (PMID 38137564, 2023). "A metanalysis was conducted to assess the role of CDKN2A mutations (in either tissue, blood, or pancreatic juices) in pancreatic cancer." (PMID 37460806, 2023). "Previous findings showed that CDKN2A methylation frequency was significantly increased in pancreatic cancer patients and was associated with worse survival in pancreatic cancer patients." (PMID 36117848, 2022). "As a typical example, in kindred with familial atypical multiple mole melanoma, the risk of pancreatic cancer, in the carriers of a germline CDKN2A mutation, is 38 times greater than in the general population, according to estimations." (PMID 36309754, 2022).
pancreatic cancer (continued). "Briefly, 29 missense CDKN2A variants affecting p16INK4A that were previously reported in patients with familial pancreatic cancer, PDAC, or reported in ClinVar as VUSs were selected." (PMID 35001868, 2022). "The molecular alterations in ASCP resemble those detected in PDA, being the loss of p16 (which is the protein that the gene CDKN2A encodes) a usual process in the first steps of the development of pancreatic cancer." (PMID 36309754, 2022). "Pathogenic germline CDKN2A variants have been identified in up to 3.3% patients with familial pancreatic cancer and up to 2.6% of patients with PDAC unselected for family history or without a family history of PDAC." (PMID 35001868, 2022). "In the case of CDKN2A gene mutation, other malignancies should also be considered, especially pancreatic cancer." (PMID 35465855, 2022). "In an MRI screening study on 79 CDKN2A mutation carriers, pancreatic cancer was diagnosed in 7 patients (9%) during a median follow-up period of 4 years." (PMID 35163129, 2022). "A highly elevated risk of carcinoma of the pancreas has been noticed in germline CDKN2A mutation carriers." (PMID 36309754, 2022). "For those subjects suffering from pancreatic cancer and bearing a CDKN2A mutation, the guidelines issued by the American Cancer of the Pancreas Screening Consortium and the American College of Gastroenterology are still the most up-to-date resources." (PMID 34442055, 2021). "Increased risk of pancreatic cancer is observed in cases with CDKN2A mutations in familial melanoma." (PMID 35154607, 2021). "Individuals with CDKN2A variants have a 70% life-time risk of developing melanoma and a 17% risk of developing pancreatic cancer up to the age of 70 years." (PMID 34476650, 2021). "An extension of this research stream should be to investigate the role of other tumor suppressing genes such as PTEN and CDKN2A as genetic regulating factors underlying EMT process in proliferation of pancreatic cancer." (PMID 33928036, 2021). "It was reported that somatic mutations of CDKN2A, a tumor suppressor factor, are present in up to 95% of pancreatic tumors." (PMID 34205170, 2021). "As pancreatic cancer approaches the low grade PanIN stage (PanIN 1A and 1B), mutations are acquired in CDKN2A gene in the form of homozygous deletions, mutations, or promoter hyper-methylation." (PMID 38107772, 2021). "Hereby, we provide a hereditary human pancreatic cancer model which enables further dissection of tumor initiation and early development starting from patient-specific CDKN2A-mutated pluripotent stem cells." (PMID 34680288, 2021). "In these families, the probability of harboring a germline CDKN2A mutation increases up to 74% in the presence of a diagnosis of pancreatic cancer." (PMID 34442055, 2021).
pancreatic cancer (continued). "Hereby, we provide a model for hereditary human pancreatic cancer that enables dissection of tumor initiation and early development starting from patient-specific CDKN2A-mutated pluripotent stem cells." (PMID 34680288, 2021). "In particular, a Swedish study found that a particular CDKN2A mutation (p.Arg112dup) confers a 43.8 times higher risk of pancreatic cancer compared to the general population." (PMID 34442055, 2021). "Further germline DNA sequencing was performed on available samples of 70 subjects aged 30 and older who were members of three kindreds in which a proband with pancreatic cancer carried the CDKN2A (47T>G) mutation." (PMID 33823155, 2021). "It has been seen that germ-line mutations in p16 have currently caused a wide range of cancers like melanoma and pancreatic carcinoma; it has also been reported that there is a remarkable association between this mutation(CDKN2A) and pancreatic neoplasia." (PMID 34711012, 2021). "CDKN2A mutations with p14 loss result in cutaneous melanoma but are also found in pancreatic carcinoma." (PMID 34203771, 2021). "Corresponding to the higher un-responsiveness of pancreatic cancer patients with KRAS mutation or CDKN2A deletion, we found that MMP14 and PKM2 were highly expressed in drug un-responsive patients." (PMID 32950968, 2020). "Previously several studies reported recurrent mutations and loss in CDKN2A in many human cancer types such as pancreatic cancer and oral squamous cell carcinoma." (PMID 32617189, 2020). "CDKN2A mutation has been demonstrated as an important event in a number of tumor types, including pancreatic cancer and gastric cancer." (PMID 32420374, 2020). "CDKN2A that encodes the tumor suppressor p16/INK4 is well known as CDKN2A germline mutations have been reported in familial forms of pancreatic cancer." (PMID 33182511, 2020). "CDKN2A, the gene encoding p16, is deleted or mutated in a wide variety of tumors, such as pancreatic cancer, esophageal cancer, and head and neck cancer." (PMID 32047552, 2020). "With regard to pancreatic cancer, DNA methylation markers, cyclin-dependent kinase inhibitor 2A (CDKN2A/p16), ras-associated domain family member 1 (RASSF1A) and neuronal pentraxin 2 (NPTX2) in cfDNA are considered diagnostic markers." (PMID 32520974, 2020). "In pancreatic cancers, CDKN2A is inactivated in ~40% of cases by deletion of both alleles, with loss associated with worse survival probability." (PMID 31608239, 2019).